MET (MET proto-oncogene, receptor tyrosine kinase)
Diseases named in the same sentence as MET in open-access papers (continued):
Sharing a sentence is not in itself a finding about the gene and the disease.
tumor (continued). "These fusions instigate ligand-independent dimerization of MET, causing continuous kinase activity that can lead to tumor formation." (PMID 38675409, 2024). "The hallmark of pRCC is germline mutations in the MET proto-oncogene, which activates MET signalling to promote tumor and cell motility." (PMID 38571885, 2024). "In a recent TATTON trial, the combination therapy of savolitinib and osimertinib showed encouraging anti-tumor activity in patients with MET-amplified/overexpressed EGFR-mutated advanced NSCLC who had previously experienced disease progression on EGFR TKIs." (PMID 38892160, 2024). "These tumours have alterations in chromosomal numbers and are associated with mutations in MET, CDKN2A, SETD2, BAP1, PBRM1, NFE2L2, and mTOR genes and have a better prognosis when compared with clear cell RCC in the organ-confined stage." (PMID 38265103, 2024). "These inhibitors target MET exon 14 skipping mutations and MET amplifications, which are involved in tumor growth and survival." (PMID 39064229, 2024). "High MET (METamp) expression, encoding the c-MET protein in humans, occurs in various tumor diseases." (PMID 39063041, 2024). "Particularly, c-MET expression levels were found to be upregulated in circulating human and mouse tumor-associated neutrophils upon inflammatory stimuli." (PMID 38909206, 2024). "Dysregulation of HGF/c-MET signaling in NSCLC is associated with tumor proliferation, angiogenesis, invasion, metastasis, and acquired drug resistance." (PMID 39201787, 2024). "This study aimed to investigate the prognostic value of c-MET-positive circulating tumor cells (cMET+ CTCs), ESR1/PIK3CA mutations, and cell-free DNA (cfDNA) concentrations in patients with hormone receptor-positive (HR+) metastatic breast cancer (mBC)." (PMID 38238761, 2024). "In summary, since its discovery as an oncogene, MET has been found to undergo mutations, amplifications, or rearrangements in a wide range of cancers, spanning from the early stages of tumor initiation to instances of therapeutic resistance and recurrence." (PMID 38675409, 2024). "By employing the MCODE plugin in Cytoscape, we identified key sub-networks within the PPI network, which included genes such as IL-10, CD3E, MET, and others that were associated with anti-tumor immune response." (PMID 38327746, 2024). "The abnormal activation of the MET/HGF pathway caused by METex14 or MET amplification is involved in the maintenance of tumor transformation and promotion of cancer cell proliferation, survival, invasion, and metastasis." (PMID 38758826, 2024). "Activation of the MET/HGF pathway has been implicated in promoting tumor invasiveness and predicting poor disease prognosis." (PMID 39123420, 2024). "This was confirmed by FISH analysis, showing a tandem duplication of MET in the clinical tumor and the loss of the duplicated region in the xenograft that leads to the CNV profile observed." (PMID 39283723, 2024). "Tumor expression and the phosphorylation of c-MET have been associated with poor survival and early distant metastases." (PMID 38473413, 2024). "Liquid biopsy has also provided an easier means of obtaining genomic information, especially upon resistance, although sensitive detection of copy number variants, including MET, fusions, and diagnosis of small-cell transformation, still require tumor tissue." (PMID 39195317, 2024). "In xenografts, both c-MET (encoded by MET) and tyrosine kinase inhibition suppressed tumor growth by inhibiting MITF." (PMID 38916046, 2024). "This rare alternative splicing event has not been described, to date, in normal human tissues, but mouse fibroblasts expressing the MET variant with the described deletion display transforming phenotypes and form tumours in immunodeficient mice." (PMID 38652103, 2024).
tumor (continued). "At the protein level, co-expression of VEGFR2 and other receptor tyrosin kinases (RTKs) such as EGFR and MET, expressed on endothelial and tumor cells, respectively, has been associated to aberrant VEGF-A expression and intrinsic resistance to BEVA." (PMID 37041632, 2023). "For example, an increased occurrence of MET exon 14 skipping mutations has been found in larger Caucasian and Chinese cohorts, which lead to a splice variant of the MET gene with increased activation of MET kinase and increased tumour growth." (PMID 37445733, 2023). "Overexpression of MET has been linked to a more aggressiveness phenotype, i.e., advanced local tumor growth, nodal spread, distant metastasis, advanced tumor stage, recurrence, and poor survival." (PMID 36260159, 2023). "As MET signalling has previously been associated with tumour progression and treatment resistance in PDAC, the authors used the multi-kinase inhibitor cabozantinib to block MET phosphorylation to overcome this PDT-mediated effect." (PMID 37627163, 2023). "In tumor cells, specific MET-related mutations have been identified to enhance catalytic efficiency." (PMID 37919751, 2023). "In this vein, many aberrant activations of the MET pathway have been determined in the tumor tissue, including MET gene amplification, point mutations, gene fusions, exon 14 skipping mutations, protein overexpression, and other activating mutations." (PMID 37400762, 2023). "CYP1A2 was identified as an antagonist of the hepatocyte growth factor/c-mesenchymal–epithelial transition factor (HGF/MET) signaling pathway, which is associated with tumor progression, survival, and metastasis." (PMID 38067357, 2023). "MET mutations have been found to be potential drivers of tumor development in RCC and hence a promising therapeutic target." (PMID 37383233, 2023). "Some studies have suggested that the modulation of the expression of PD-L1 on tumor cells affects antitumor immunity and that MET signaling is associated with the expression of PD-L1 on tumor cells." (PMID 37258621, 2023). "MET overexpression increases ligand-independent phosphorylation and activation of signaling pathways, and it has been linked to metastases, enhanced tumor invasion, and poor survival." (PMID 37296895, 2023). "This is crucial since MET amplification, overexpression, and activation in tumor tissue from cancer patients have been linked to poor overall survival." (PMID 37400762, 2023). "In a study on the comprehensive molecular characterization of PRCC, alteration of the MET gene (mutation, splice variant, or gene fusion) or gain of chromosome 7 copy number was identified in 81.3% of Type 1 tumor." (PMID 37283291, 2023). "A 65-year-old never-smoking white male with advanced sarcomatoid NSCLC harboring a MET exon 14 skipping mutation and with a PD-L1 tumor proportion score of 80% was initiated on combination chemotherapy plus ICI therapy after progression on a MET inhibitor." (PMID 35871685, 2022). "CircBFAR acts as molecular sponge for miR-34b-5p, leading to upregulation of mesenchymal–epithelial transition factor (MET), causing tumor progression in PDAC." (PMID 35158814, 2022). "High MET expression has also been found to be associated with poor loco-regional tumor control and increased metastasis after post-operative chemoradiotherapy in patients with HPV (–) HNSCC." (PMID 36261806, 2022). "It is possible that DNM3 mutations promote tumor cell growth through the activation of the c-MET/STAT3 pathway." (PMID 36528667, 2022). "Tumor specimens from patients with acquired drug resistance showed high expression of HGF in the context of MET amplification and the T790M mutation." (PMID 35840984, 2022).
tumor (continued). "Numerous studies reported that MET deregulation by overexpression, activating mutations, splicing variants and amplification is implicated in tumour development and progression, positioning MET as therapeutic target for the treatment of cancer, including HCC." (PMID 35748700, 2022). "The circRNA circBFAR is involved in PDAC tumor progression causing proliferation and invasiveness via the cBFAR/miR-34b-5p/MET axis." (PMID 35158814, 2022). "Using targeted proteomics tools within a set of various cancer models we describe here the discovery and characterization of a composite phosphorylation signature associated with tumor addiction to four distinct oncogenes, MET, EGFR, ALK and BRAF." (PMID 36494469, 2022). "Out of six assessed candidate molecules, c-MET, a receptor tyrosine kinase encoded by the MET gene, turned out to be the most seminal target, providing a plausible red thread between both tumor tissue and cell lines." (PMID 35406455, 2022). "Aberrant activation of mesenchymal-epithelial transition factor (MET) causes c-MET dimerization, autophosphorylation, and kinase activity that are essential for malignant transformation, facilitating tumor progression and metastasis." (PMID 36457016, 2022). "c-MET has been reported to be associated with most human cancers, which can stimulate various downstream signaling pathways in tumor cells, such as PI3K/AKT, Wnt/β-catenin, JAK/STAT, Ras/MAPK, and SRC." (PMID 35236826, 2022). "Dysregulation of MET signal is closely associated with the tissue grade, treatment resistance, tumor recurrence and poor prognosis." (PMID 35935338, 2022). "The clinical evidences have been obtained from breast cancer patients, where after intra tumor injection, tumors displayed necrosis, loss of c-MET and infiltration of macrophages." (PMID 35081970, 2022). "Studies have consistently shown that MET overexpression is a negative prognostic indicator in a variety of malignancies, and activation of the HGF-MET axis was associated with the drug resistance of tumor cells." (PMID 36142142, 2022). "MET is a tyrosine kinase receptor encoding hepatocyte growth factor, which can promote the proliferation, migration, and invasion of tumor cells by binding HGF ligand." (PMID 35190747, 2022). "EGFR mutation is usually connected with low PD-L1 expression, while KRAS and MET alterations are associated with higher PD-L1 tumour expression." (PMID 35329956, 2022). "All MET-amplified tumors had microsatellite stable status, and 8 had a high tumor mutational burden." (PMID 36483096, 2022). "Given the lack of METΔex14 cell lines available, we expanded our analysis to include publicly available RNA-seq data from tumours with either high-grade wildtype MET amplification (n = 6) or METΔex14 mutations (n = 8)." (PMID 35326531, 2022). "The association of MET-TLs with MET-expressing tumor cells is an Nb density-dependent process; however, highly conjugated surfaces lead to a decrease in cell specificity." (PMID 36499301, 2022). "Conversely, some authors reported that c-MET overexpression was associated with depth of tumor invasion and lymph node metastasis." (PMID 35076580, 2021). "The c-MET oncogene activates different intracellular signaling pathways associated with a high clonogenic and tumorigenic potential of tumor cells." (PMID 33919702, 2021). "This tight regulation is lost within HNSCC and abnormal, activated or overexpressed MET causes tumor progression, invasion and metastasis." (PMID 33919702, 2021). "c‐Met is a receptor tyrosine kinase expressed on the surface of epithelial and endothelial cells and is activated in various tumor types as a result of gain‐of‐function MET mutations, MET amplification, and c‐Met overexpression." (PMID 33675179, 2021).
tumor (continued). "Capmatinib is a selective MET inhibitor that has been granted accelerated FDA approval for patients with NSCLC whose tumours harbour MET exon 14 mutation." (PMID 33526881, 2021). "Patients were assigned to cohorts based on previous lines of therapy and MET status (MET exon 14 skipping mutation or MET amplification according to gene copy number in tumor tissue)." (PMID 34425853, 2021). "Excessive c-MET activation in advanced cancers can cause tumor cell proliferation, motility, migration, and invasion." (PMID 34504652, 2021). "First, we found that overexpressions of c-MET/EGFR were associated with the infiltration of tumor immune cells and cancer-associated fibroblasts, and were of prognostic relevance in CRC cohorts." (PMID 34512327, 2021). "When interrogating DNA from the primary PTC and metastatic PDTC using the Oncomine Solid Tumor Panel, a missense variant in exon 2 of the MET gene (c.1076G > A, p.Arg359Gln) was found in both the primary tumor and metastasis." (PMID 34389035, 2021). "Analysis of circulating tumor DNA (ctDNA) by next-generation sequencing (NGS) indicated a loss of MET amplification status." (PMID 35693217, 2021). "Different types of MET mutations differentially affected tumor growth and displayed different sensitivities to cisplatin and tyrosine kinase inhibitors." (PMID 34439385, 2021). "While HGF/MET signaling has been traditionally implicated in tumor cell proliferation, survival, motility and epithelial-to-mesenchymal transition, recent data point at its pivotal role in controlling glucose metabolism in cancer cells." (PMID 34200749, 2021). "RTKs such as c-MET are often overexpressed in locally advanced HNSCCs and are associated with therapy resistance and tumor relapse." (PMID 33919702, 2021). "Predictive biomarkers include activating mutations in EGFR, BRAF, KRASG12C, and ERBB2, rearrangements in ALK, ROS1, RET, and NTRK, MET amplification or exon 14 skipping mutations, PD-L1 expression, and tumor mutational burden." (PMID 34425853, 2021). "PDXs demonstrated response to radiation, response to selumetinib in tumors harboring KRAS G12C mutations and response to savolitinib in a tumor with MET exon 14 skipping mutation." (PMID 33510214, 2021). "In this review, the c-MET-HGF pathway has also been implicated in altered IDO expression by tumor cells." (PMID 32117721, 2020). "MET overexpression in tumor tissue samples was associated with worse prognosis in patients receiving sorafenib." (PMID 32492896, 2020). "This in vivo LC suppressive effect was also associated with significant inhibition of the c-MET activation in tumor cell lysates collected from treated animals at the experiment end as compared to the vehicle control group." (PMID 32545325, 2020). "These mutations cause lower rates of c-MET ubiquitination and degradation, therefore leading to amplified proliferation pathways and more aggressive tumor characteristics." (PMID 33153004, 2020). "Aberrant cMet expression or constitutive activation of the cMet signaling pathway due to amplification, overexpression of its ligand HGF, and mutation in MET is seen in many human tumor types and is the rationale for developing cMet‐targeting therapeutics." (PMID 31736230, 2020). "Recently, a study in cfDNA obtained from plasma of different tumor types showed that detection of MET alterations (amplification and point mutations) by liquid biopsy was feasible using the Guardant360 NGS panel." (PMID 32102486, 2020). "Aberrant MET activity has been implicated in acquired tumor cell resistance to treatment with EGFR-targeted therapy and, more recently, resistance to immunotherapy." (PMID 33437521, 2020). "The matched tumor tissue overexpressed c‐MET, indicating a mechanism underlying gefitinib resistance." (PMID 32633046, 2020). "In a study of more than 10,000 cases from 33 cancer types, high tumor expression of a germline variant in an oncogene (AR, MET, RET, CBL, and PTPN11) was found in 33 patients." (PMID 32295625, 2020).
tumor (continued). "A separate study of 155 resected NSCLC tumor samples found MET activation was associated with PD-L1 expression and demonstrated that in NSCLC cell lines c-MET signaling directly induces PD-L1 expression." (PMID 32117721, 2020). "HGF overexpression further affects the activation of MET and its downstream signaling pathways, thereby causing tumor resistance to MET inhibitors." (PMID 32435640, 2020). "Currently, the reported reasons for EGFR-TKI acquired resistance are EGFR 20 exon T790M mutation, MET amplification, and phenotypic transformation of tumor cells." (PMID 33056982, 2020). "In tumour cells, MET can be activated in a ligand-independent manner by mutating, amplifying or overexpressing the MET gene." (PMID 32295618, 2020). "Altogether, our investigation demonstrates that Brg1 can function as a tumor suppressor, and loss of Brg1 is able to cooperate with c-MET or NRASV12 to induce liver tumor development in mice." (PMID 32019910, 2020). "In contrast, MET deficiency markedly inhibited the tumor growth in the C57BL/6 mice inoculated with either H22 cells or Hepa1-6 cells." (PMID 32764535, 2020). "MET gene amplification, mutation, and overexpression have been reported in various cancers and are strongly implicated in tumor growth and proliferation, tumorigenic transformation, anti-apoptosis effects, resistance mechanisms, angiogenesis, and invasiveness." (PMID 32549194, 2020). "This is particularly important as MET amplification/over-expression and activation, when present in cancer patients’ tumour tissue, have been associated with poor overall survival." (PMID 33149187, 2020). "The proto-oncogene MET encodes receptor tyrosine kinase c-Met that promotes tumor development and progression by regulating multiple downstream events including STAT3/c-Myc, PI3K/AKT, Ras/MAPK, JAK/STAT, SRC and Wnt/β-catenin." (PMID 32726914, 2020). "Dysregulation of c-MET signaling–mediated proliferation, migration, invasion and angiogenesis through overexpression of MET and amplification or mutation of the MET gene has been widely demonstrated in oncogenic processes across multiple tumor types." (PMID 32545325, 2020). "Overall, MET inhibitors affect MET expression in tumor-associated immune cells and are a potential mechanism for drug resistance." (PMID 32435640, 2020). "MET is a tumor-associated antigen facilitating tumor cell recognition by CD8+ cytotoxic T cells, which triggers immune system activation." (PMID 33034614, 2020). "In both canine and human tumour cells, overexpression of MET causes the activation of different signalling cascades, resulting in the growth, proliferation, invasion and survival of tumour cells." (PMID 33008041, 2020). "Previous reports indicated that dysregulation of the HGF/c-MET pathway was found in multiple tumor types and was associated with unfavorable outcomes." (PMID 30782177, 2019). "Our more recent works showed that a nanoparticle-mediated plasmid encoding HGFK1 gene (H1/pHGFK1) exerts anti-tumor and radiosensitive activities through inhibiting MET signaling pathway, an important cancer cells “stemness” regulator in glioblastoma." (PMID 31426831, 2019). "In the 39 PTC with distant metastasis, 36% harboured MET mutation, as opposed to 20% of the 20 control PTC, thus indicating a strong association of MET exon 2 or 14 mutations with tumor progression." (PMID 31040922, 2019). "The identification of increased MET copy number within tumour cells is increasingly important to stratify those tumours and patients which are susceptible to treatment targetting MET kinase inhibition." (PMID 31613934, 2019). "The c-Met, and its ligand HGF have been associated with tumor formation and progression to metastasis, with MET gene often overexpressed or mutated." (PMID 29455657, 2018). "The pRCC is associated with germline mutations of MET proto-oncogene, and these mutations activate MET signaling to promote tumor and cell motility." (PMID 29662646, 2018).